PMP22 (peripheral myelin protein 22)
Description:
Might be involved in growth regulation, and in myelinization in the peripheral nervous system.
Synonyms: GAS-3; GAS3; HNPP; Sp110; HMSNIA; CIDP; CMT1A; CMT1E; DSS
Tractability: Small molecule: it belongs to a druggable protein family. Antibody: UniProt places it where antibodies can reach, with high confidence; its Gene Ontology location is reachable by antibodies, with high confidence; UniProt predicts a signal peptide or a membrane-spanning region. PROTAC: UniProt records ubiquitination sites on it; a small molecule that binds it is known.
Gene: Protein-coding gene on chromosome 17 (15,229,773 to 15,272,292, reverse strand). Ensembl gene ENSG00000109099.
Subcellular location: Cell membrane
Pathways (Reactome):
Developmental Biology: EGR2 and SOX10-mediated initiation of Schwann cell myelination
Gene Ontology:
Molecular function: protein binding
Biological process: apoptotic process; bleb assembly; chemical synaptic transmission; myelin assembly; peripheral nervous system development; cell differentiation; myelination; negative regulation of cell population proliferation; negative regulation of neuron projection development; nervous system development
Cellular component: plasma membrane; bicellular tight junction; compact myelin; membrane; synapse
Genetic constraint (gnomAD): Loss-of-function variants: 2 observed, 16.83 expected, observed/expected ratio (o/e) 0.12, 90% interval 0.048 to 0.37. The upper end of that interval is the gene's LOEUF score, 0.37, which puts it in group 1 of 6, group 1 being the genes least tolerant of losing a copy. Missense variants: 169 observed, 195.87 expected, observed/expected ratio (o/e) 0.86, 90% interval 0.76 to 0.98. Synonymous variants: 95 observed, 85.07 expected, observed/expected ratio (o/e) 1.12, 90% interval 0.94 to 1.32.
Gene-disease validity (ClinGen):
ClinGen rates the evidence that PMP22 causes each of these diseases.
Charcot-Marie-Tooth disease type 1A (autosomal dominant): Definitive. Charcot-Marie-Tooth disease type 1A (CMT1A) is a type ofinherited neurological disorder that affects the peripheral nerves.
hereditary neuropathy with liability to pressure palsies (autosomal dominant): Definitive. Hereditary neuropathy with liability to pressure palsies (HNPP) is an inherited peripheral nerve disorder characterized by recurrent mononeuropathy usually triggered by minor physical activities.
Homologues: Orthologues: macaque PMP22 (99% identical), dog PMP22 (93% identical), guinea pig PMP22 (93% identical), pig PMP22 (89% identical), rat Pmp22 (87% identical), mouse Pmp22 (86% identical), tropical clawed frog pmp22 (78% identical), zebrafish pmp22b (66% identical), zebrafish pmp22a (50% identical). Paralogues in human: EMP2 (45% identical), EMP3 (42% identical), EMP1 (39% identical), GSG1L2 (28% identical), LIM2 (26% identical), GSG1L (24% identical), TMEM202 (22% identical), GSG1 (21% identical), CLDND2 (21% identical), NKG7 (17% identical).
Diseases named in the same sentence as PMP22 in open-access papers:
PMP22 is named in the same sentence as 166 diseases in open-access papers, as found by Europe PMC text mining. Sharing a sentence is not in itself a finding about the gene and the disease. The quoted sentences say what the papers report.
neuropathy (78 papers, 2005 to 2026). A disorder affecting the nervous system that manifests with pain, tingling, numbness, and/or muscle weakness. "The hypertrophic and demyelinating changes seen in RLS mirror those observed in other PMP22-related neuropathies, linking the molecular alterations caused by the 17p11.2 duplication to structural abnormalities in peripheral nerves." (PMID 41595476, 2026). "Duplication of PMP22 causes CMT1A, a progressive dysmyelinating neuropathy that typically presents in childhood and leads to steadily worsening motor and sensory deficits, often resulting in lifelong disability." (PMID 41400104, 2026). "Another group of neuropathies associated with large deletions in the PMP22 gene are HNPP (Hereditary neuropathy with liability to pressure palsy)." (PMID 41300731, 2025). "The identification of pathogenic variants in well-established neuropathy-associated genes such as PMP22, MME, MPV17, and HINT1 confirms the value of CES, particularly when traditional single-gene screening is inconclusive." (PMID 41509941, 2025). "Our findings indicate that myelin abnormalities and altered signal propagation in the peripheral arm of the auditory nerve are likely causes of auditory deficits in patients with PMP22-linked neuropathies." (PMID 38378628, 2024). "Although PMP22-linked monogenic human neuropathies are clear, the protein's function is not fully understood." (PMID 38378628, 2024). "Herein, we first report a patient with occulted CMT1A due to a mutation in the peripheral myelin protein 22 (PMP22) gene who developed severe recurrent neuropathy after a previous SARS-CoV-2 vaccination and subsequent COVID-19 infection." (PMID 38651106, 2024). "Patients diagnosed with PMP22-linked neuropathies, such as Charcot–Marie–Tooth (CMT) disease, often have the initial presentation in auditory and balance deficits." (PMID 38378628, 2024). "PMP22-linked neuropathies are classified as type 1 HPNs, with the primary lesion being demyelination, but axonopathy and distal neurodegeneration frequently accompany the disease." (PMID 38378628, 2024). "In this paragraph, we will provide an overview of these strategies and we will finally focus on the CMT1A neuropathy, due to the PMP22 gene duplication, the most frequent mutation in CMT that accounts for 50–60% of all CMTs." (PMID 38678519, 2024). "Pmp22 overexpression in CMT1A causes neuropathy by a partial loss of PI3K/Akt/mTOR signaling in Schwann cells, which should be ameliorated by the pharmacologic inhibition of PTEN." (PMID 38383802, 2024). "As a consequence, the CMT-class neuropathy caused by heterozygous WT/T118M PMP22 expression is similar to but even more mild than the HNPP phenotype seen for haploinsufficient (WT/null) patients." (PMID 36581210, 2023). "We undertook to compare the formation of intracellular aggregates by T118M PMP22 to WT PMP22 and L16P PMP22, the latter of which causes severe neuropathy (DSS)." (PMID 36581210, 2023). "The overexpression of PMP22 in animal models is sufficient to cause neuropathy, suggesting that increased dosage of PMP22 is the main contributing factor in CMT1A pathology." (PMID 35501630, 2022). "Approximately 50% of all CMT cases are caused by mutations in PMP22, and abnormalities of PMP22-related neuropathies can be principally divided into 2 types." (PMID 33726003, 2021). "De novo dominant variants predicted to affect function have been well reported in association with early-onset neuropathies in PMP22, MPZ and EGR2 [20, 21,]." (PMID 29511323, 2018). "Missense mutations in PMP22 cause a variety of neuropathies, including Charcot-Marie-Tooth disease (CMT) and hereditary neuropathy with liability to pressure palsies (HNPP)." (PMID 30675404, 2018). "The aim of present study is to investigate the frequency and spectrum of PMP22 point mutations in cohorts of Taiwanese patients with CMT or HNPP-like neuropathy." (PMID 29127354, 2017).
neuropathy (continued). "Mutations in the peripheral myelin protein 22 (PMP22) gene are the most common cause of inherited neuropathies, and different types of PMP22 mutations lead to diverse phenotypes." (PMID 29127354, 2017). "Because abnormal protein aggregates can interfere with fundamental cellular functions, enhancement of chaperones should be considered as therapy for PMP22-linked neuropathies." (PMID 25694550, 2015). "Nevertheless, the observed positive effects of elevated HSP70 in preventing the accumulation of undegraded proteasome substrates support further study of HSP90 inhibitors in models of PMP22-linked neuropathies." (PMID 25694550, 2015). "The third group is composed of neuropathies related to point mutations in the PMP22 gene and is classified as CMT1A or CMT1E." (PMID 24646194, 2014). "Missense mutations in PMP22 cause variable syndromes similar to that found with HNPP (heredity neuropathy with liability to pressure plates), suggesting that they yield a loss of PMP22 function." (PMID 25400662, 2014). "Together our studies show that a number of ongoing pathogenic mechanisms contribute to the progression of the neuropathy in C22 mice, which initiates with abnormal expression of PMP22." (PMID 24175617, 2013). "Compared with the degradative mechanisms, it is more difficult to dissect the role of chaperones in the pathogenesis of PMP22-linked neuropathies." (PMID 24175617, 2013). "The rearrangements cause altered dosage of PMP22 that subsequently results in neuropathy; overexpression causes CMT1A whereas underexpression (i.e., haploinsufficiency) leads to HNPP." (PMID 16444292, 2005). "Besides null alleles, also heterozygous PMP22 mutations can lead to HNPP-like neuropathy possibly due to reduced trafficking of the mutant protein to the Schwann cell plasma membrane." (PMID 38383802, 2024). "Although we have found a significant amelioration of demyelination-associated neuropathy in C22 mice by targeted mutagenesis of TATA-box of PMP22, administration of therapeutic CRISPR at p6 could be a prevention rather than treatment." (PMID 31713617, 2020). "CMT1A and CMT1B are neuropathies caused by genetic abnormalities in peripheral myelin protein 22 and myelin protein zero, respectively, which are the main myelination-associated proteins in Schwann cells, and commonly show progressive SNHL starting in adolescence." (PMID 32453729, 2020). "As observed in our study, hearing loss associated to neuropathy due to PMP22 is very variable." (PMID 31393079, 2019). "Sequencing of 72 neuropathy genes showed one copy of a pathogenic variant, T118M in the PMP22 gene." (PMID 30675404, 2018). "Age-related decrease in chaperone response could then contribute to the progression of PMP22-linked neuropathies." (PMID 25694550, 2015). "Therefore, changes in degradative and chaperone mechanisms with age likely impact the progression of hereditary nerve disorders, particularly where protein misfolding is involved such as in PMP22-linked neuropathies." (PMID 24175617, 2013). "Therefore, PMP22 point mutations only accounted for 0.7% (1/138) of overall HNPP-like neuropathy and 1.9% (1/52) of HNPP-like neuropathy with unknown genetic diagnosis in Taiwan." (PMID 29127354, 2017). "Macroautophagy (hereafter referred to as autophagy) is also critical in PMP22-linked neuropathies as autophagosomes accumulate near protein aggregates within neuropathic Schwann cells and under permissive conditions, activating autophagy clears the misfolded PMP22." (PMID 24175617, 2013). "However, some CNVs can be inherited in a Mendelian way: Charcot-Marie-Tooth disease type 1A is a dominant neuropathy associated to a duplication of the gene for peripheral myelin protein 22 (PMP22), whereas a deletion of the b-globin gene cluster is responsible for the recessive anemia-thalassemia." (PMID 21358991, 2010).
neuropathy (continued). "Advances in molecular genetics have identified key causative genes, including PMP22, MPZ, MFN2, TTR, EGR2, and CX32 (GJB1), which are implicated in Charcot–Marie–Tooth disease, Dejerine–Sottas syndrome, and related neuropathies." (PMID 41595476, 2026). "In contrast, deletion of PMP22 causes HNPP, a milder disorder characterized by transient, focal neuropathies triggered by mechanical compression, with onset typically in adolescence or adulthood." (PMID 41400104, 2026). "About the gender of patients, where we noted a higher incidence of PMP22-related neuropathies in males (53.8%)." (PMID 41300731, 2025). "Eligible studies reported genetically confirmed PMP22-related neuropathies with clinical and/or neurophysiological data." (PMID 41300731, 2025). "PMP22-related neuropathies constitute a heterogeneous group of diseases, as evidenced by the data we have collected in this systematic review of the literature." (PMID 41300731, 2025). "In Charcot–Marie–Tooth Disease Type 1A (CMT1A), a common duplication of the PMP22 gene leads to overproduction of the PMP22 protein, which disrupts the structure and function of myelin in peripheral nerves, resulting in neuropathy." (PMID 39757377, 2025). "We would like to emphasize that HNPP has a higher incidence in males than that seen in other forms of PMP22-related neuropathies." (PMID 41300731, 2025). "We collected data from 127 studies, including a total of 4493 patients with PMP22-related neuropathies." (PMID 41300731, 2025). "Further studies are warranted on the behavior of plasma biomarkers in rare PMP22-related neuropathy." (PMID 37606798, 2023). "For example, L16P PMP22, which causes DSS (severe neuropathy), traffics to the PM of Madin–Darby canine kidney (MDCK) cells with an efficiency of <2%." (PMID 36581210, 2023). "After validating AAV9-miR871 in vivo PNS biodistribution and PMP22 and Pmp22 gene silencing efficacy, we proceeded with a proof-of-concept treatment trial at early stages of neuropathy in the CMT1A mouse model." (PMID 35579942, 2022). "Demyelinating neuropathies have better yield compared to axonal or mixed neuropathies, even after PMP22 deletion or duplications have been excluded." (PMID 36313509, 2022). "Since transgenic mice carrying additional copies of pmp22 displayed severe hypomyelination neuropathy, expressed embryonic SC markers, and incorporated BrdU, impaired SC differentiation into the myelinating status has been also proposed." (PMID 35327648, 2022). "Further CMT1A models have been generated in mice, though they needed several extra copies of the Pmp22 gene to induce overexpression of the Pmp22 protein and thus the neuropathy." (PMID 34573256, 2021). "Taken together, these data demonstrate that siRNA PMP22-SQ NPs induce remarkable recovery from CMT1A neuropathy, with the improvement of motor and electrophysiological parameters reaching levels observed in WT mice." (PMID 33750896, 2021). "One CMT1 patient with PMP22 duplication and MPZ variant (c.286A>C, p.K96Q) exhibited moderate neuropathy with infantile onset, while her father possessing MPZ variant was mildly affected with adolescence onset." (PMID 35153971, 2021). "Any strategy aimed at reducing the PMP22 gene dosage (or RNA/protein PMP22 production) would constitute and efficacious strategy to treat the neuropathy." (PMID 34573256, 2021). "We conducted a study to provide the most detailed description of PMP22-related neuropathy in mainland China." (PMID 32719652, 2020). "In conclusion, PMP22 point mutations are uncommon causes of demyelinating CMT and HNPP-like neuropathy." (PMID 29127354, 2017). "This study delineates the clinical and molecular features of PMP22 point mutations in Taiwan, expands the spectrum of PMP22 point mutations, and emphasizes its role in demyelinating CMT and HNPP-like neuropathy." (PMID 29127354, 2017).
neuropathy (continued). "This study delineates the clinical and molecular features of PMP22 point mutations in Taiwan, and emphasizes their roles in demyelinating CMT or HNPP-like neuropathy." (PMID 29127354, 2017). "We found a PMP22 point mutation in one out of 52 HNPP-like neuropathy patients with unclear causes, whom were chosen from 138 patients with HNPP-like phenotype after excluding PMP22 deletion." (PMID 29127354, 2017). "While PMP22 is known to be expressed in a number of different cell types, nerve transplantation studies established that the neuropathy initiates within the Schwann cells." (PMID 24175617, 2013). "Previous studies have examined behavioral, electrophysiological and morphological aspects of the neuropathy in PMP22-overexpressing C22 mice over a 1.5 year life-span and reported prominent axonal pathology." (PMID 24175617, 2013). "Similar to previous findings in the TrJ mouse model of PMP22 neuropathies, overproduction of PMP22 in the C22 mice does not elicit an ER stress response." (PMID 24175617, 2013). "The UPS is a particularly important mechanism in PMP22 neuropathies, as the proteasome is responsible for the degradation of newly synthesized, short-lived PMP22." (PMID 24175617, 2013). "To determine the incidence of such structures with neuropathy progression, we immunostained nerve sections from 2- and 12-month-old Wt and C22 mice with a mixture of anti-PMP22 antibodies that recognizes both the mouse and human protein." (PMID 24175617, 2013). "Ascorbic acid reduced the severity of neuropathy in transgenic mice overexpressing PMP22, an animal model of human CMT1A, compared with untreated mice." (PMID 21393063, 2011). "Ascorbic acid reduced the severity of neuropathy in transgenic mice overexpressing peripheral myelin protein 22 (PMP22), a model of Charcot–Marie–Tooth disease type 1A (CMT1A) associated with the PMP22 duplication." (PMID 21393063, 2011). "CMT1A rodent models with pmp22 over-expression, have been established to understand and treat this neuropathy." (PMID 19534778, 2009). "A rodent model for the progressive human neuropathy HMSN1A is the PMP22 C22 transgenic mouse that harbours seven copies of the human PMP22 gene in its genome." (PMID 15762989, 2005). "Being a neuropathy, PMP22 C22 mice can be used as reference animals that display a muscle phenotype without harbouring intrinsic muscle defects." (PMID 15762989, 2005). "Notably, two patients exhibited digenic inheritance involving MFN2 and either PMP22 or SOD1, highlighting the genetic complexity underlying inherited neuropathies." (PMID 41030121, 2026). "Clinicians should screen for RLS in PMP22-related neuropathies and consider symptomatic management." (PMID 42052752, 2026). "The pathophysiology of RLS mirrors that of other PMP22-related neuropathies." (PMID 41595476, 2026). "Among point mutations, those on PMP22 are not the most frequent cause of neuropathies described in this systematic review, but they still constitute a significant proportion of our sample (4.8%)." (PMID 41300731, 2025). "The fact that some nerves are not evoked, both motor and sensory, could lead to the mistaken belief that some PMP22 neuropathies are often axonal." (PMID 41300731, 2025). "As a consequence of an inequal crossing over event at the meiotic cell division, CMT1A patients carry three copies of the PMP22 gene whereas the reciprocal event, the PMP22 gene deletion, is associated with the HNPP neuropathy (Hereditary liability to pressure palsies)." (PMID 38678519, 2024). "The second most common gene with pathogenic findings detected by SV-analysis was PMP22, seen in eight patients with Charcot–Marie-Tooth type 1A (CMT1A, OMIM #118220) and one patient with neuropathy, hereditary, with liability to pressure palsies (HNPP, OMIM #162500)." (PMID 37273706, 2023).